LMNA (lamin A/C)
Diseases named in the same sentence as LMNA in open-access papers (continued):
Sharing a sentence is not in itself a finding about the gene and the disease.
premature aging syndrome (29 papers, 2011 to 2025). Changes in the organism associated with senescence, occurring at an accelerated rate. "Many of these diseases are caused by mutations in the gene for lamin A/C (LMNA) and affect primarily the muscles, the peripheral nerves, and the adipose tissue or cause systemic diseases such as premature aging syndromes." (PMID 36899919, 2023). "Hutchinson–Gilford progeria syndrome (HGPS) is a rare premature aging syndrome caused by a dominant mutation in the LMNA gene." (PMID 36139359, 2022). "Since these premature aging syndromes share an altered lamin A/C protein, it has been proposed that mutated lamin A/C has a negative impact on the homeostasis of MSCs, the natural progenitors of osteoblasts, leading to the observed abnormal bone phenotypes." (PMID 32466483, 2020). "HGPS is a rare premature-aging disease caused by a dominant de novo point mutation in the LMNA gene, resulting in the expression of a mutant form of lamin A, also known as progerin." (PMID 31344897, 2019). "Mutations in the nuclear structural protein LMNA cause the premature aging syndrome Hutchinson–Gilford progeria, and aberrant splicing of LMNA is implicated in normal aging." (PMID 24112369, 2014). "Mutations in the LMNA gene cause a variety of diseases, from muscular dystrophy and lipodystrophy to systemic diseases such as premature aging syndromes." (PMID 22783988, 2012). "The LMNA gene is associated with a wide spectrum of disorders, including premature aging syndromes." (PMID 41393291, 2025). "Mutations in LMNA (lamin A/C) cause a premature aging syndrome linked to cardiovascular defects." (PMID 36989130, 2023). "Indeed, several LMNA mutations affect bone tissue homeostasis and lead to a pathological condition, such as premature aging syndromes." (PMID 32466483, 2020). "A recently identified group of premature aging syndromes was related to mutations of the LMNA gene." (PMID 30705772, 2019). "Mutations in human LMNA cause a spectrum of >15 rare genetic diseases that affect different tissues such as skeletal muscle, cardiac muscle, adipose tissue, bone and peripheral neurons, and also cause premature ageing syndromes." (PMID 23451281, 2013). "Mutations of LMNA gene could cause premature aging syndromes." (PMID 31253764, 2019). "In HGPS, genetic mutations in the LMNA or ZMPSTE24 gene lead to defective processing of prelamin A, resulting in premature aging syndromes." (PMID 37256358, 2023). "Hutchinson–Gilford progeria syndrome (HGPS), one of the most severe premature aging syndromes, is caused by mutations in LMNA, which encodes lamin A/C." (PMID 37174634, 2023). "It is also important to mention that premature aging syndromes including Hutchinson-Guilford progeria syndrome (HGPS), atypical Werner syndrome/atypical progeria, mandibuloacral dysplasia and restrictive dermopathy are also associated with LMNA mutations." (PMID 36552829, 2022). "Therefore, our novel results in LMNA-KO rabbits suggested that premature aging syndrome is a complex disorder with combined pathogenesis affecting different tissues in the body." (PMID 30705772, 2019). "In this study, LMNA deficient rabbits, although not carrying human specific LMNA mutations, such as G608G (GGC>GGT), E145K (GAG>AAG), and G608S (GGC>AGC), develop several features of human premature aging syndrome and may therefore represent a promising model of premature aging syndrome." (PMID 30705772, 2019).
heart failure (28 papers, 2008 to 2025). Inability of the heart to pump blood at an adequate rate to meet tissue metabolic requirements. "LMNA mutation carriers have increased risk of sudden death due to cardiac and vascular events including arrythmias, heart failure and thromboembolic disease." (PMID 41165919, 2025). "LMNA mutations carry a poor prognosis, as cardiolaminopathies are associated with increased risk of arrythmias, sudden cardiac death, and worsening heart failure as well as increased need for cardiac transplantation due to rapid disease progression." (PMID 39411178, 2024). "Heart failure is linked to disrupted mechanotransduction, where LMNA mutations affect nuclear integrity, impacting the response to extracellular matrix signals and the environment." (PMID 38539233, 2024). "EDMD2 caused by mutations in LMNA leads to more severe ventricular dysfunction and heart failure compared with emerin-deficient EDMD1." (PMID 37940872, 2023). "Variant‐positive individuals had a borderline increase in the risk of progressive heart failure and life‐threatening ventricular arrhythmias, with the highest risk in carriers of variants in desmosomal genes and lamin A/C independent of LV ejection fraction." (PMID 39129193, 2024). "Patients with DCM who carry pathogenic variants in the LMNA, RBM20, and DSP genes are at higher risk for heart failure progression and may require heart transplantation." (PMID 38999368, 2024). "For example, LMNA K219T missense mutation causing severe DCM and heart failure with conduction system disease does not lead to obvious changes in lamin A/C levels in K219T iPSC-CMs." (PMID 36899919, 2023). "Altogether, these data suggest that a putative deregulation of the cell cycle during late heart development in LMNA Δ8–11 −/− mice might be at the origin of sudden death by heart failure during postnatal growth." (PMID 33917623, 2021). "However, it remains unknown how mutations of the LMNA gene induce DCM and heart failure through intracellular structural changes, including dysplasia of the sarcomere." (PMID 37058558, 2023). "Considering the possible interaction between LMNA and BICD2 and the heart failure symptoms of BICD2 mutant patients, we hypothesized that the homozygous variant (NM_001003800.1:c.2429G > A) in the C-terminal region of BICD2 would be a candidate DCM-causative variant in this family." (PMID 36068540, 2022). "However, here we detect distinct myocardial transcriptomic profiles in patients affected with different genetic cardiomyopathies in refractory heart failure (stage D) stratified by the affected genes (LMNA, PKP2, RBM20 and TTN) and not based on the clinical phenotype (DCM or ARVC)." (PMID 33260757, 2020).
congenital muscular dystrophy (25 papers, 2016 to 2024). A muscular dystrophy that is characterized by diminished muscle tone (hypotonia), progressive muscle weakness and degeneration (atrophy), abnormally fixed joints, spinal rigidity, and delays in reaching motor milestones such as sitting or standing unassisted. "The two patients assessed showed a different clinical phenotype, an atypical progeroid Werner’s syndrome (Pt 1), and a congenital muscular dystrophy (Pt 2), respectively, as a consequence of missense mutations in different domains of the LMNA gene." (PMID 39769130, 2024). "In 2011, Bertrand and colleagues created the Lmna ΔK32 knock-in mouse; this strain harbors a severe congenital muscular dystrophy (L-CMD) mutation that leads to the loss of lysine 32 in the N-terminal domain of LMNA." (PMID 29619865, 2018). "Additionally, mutations in the N-terminal part of the 1A subdomain of lamin A/C (LMNA) cause congenital muscular dystrophy or Emery–Dreifuss muscular dystrophy (MIM, #181350)." (PMID 36497166, 2022). "We recently identified one particular lamin A mutant, LMNA p.R388P, that is responsible for congenital muscular dystrophy (L-CMD)." (PMID 28441765, 2017). "Muscle laminopathies may associate cardiac disease at any age and range from congenital muscular dystrophy (LMNA-related congenital muscular dystrophy, or L-CMD) to late-onset manifestations (limb–girdle muscular dystrophy 1B, or LGMD1B; and autosomal-dominant EDMD)." (PMID 36968203, 2023). "LMNA mutations are responsible for a wide variety of pathologies, including Emery–Dreifuss (EDMD) and LMNA-related congenital muscular dystrophies (L-CMD) without clear genotype–phenotype correlations." (PMID 32244403, 2020). "In addition, here we also showed that cell–cell contact failed to inhibit YAP nuclear localization and activity in LMNA mutant cells from LMNA-related congenital muscular dystrophy (L-CMD), contrary to what was observed in our wild-type (WT) and LMNAH222P cells and in other non-cancer cells." (PMID 32231000, 2020). "The patient with the combined LMNA and TMEM201 mutations had a very early age of onset (1 year), suggesting that both mutations contribute to the more severe (congenital) phenotype as the LMNA mutation has not been associated with congenital muscular dystrophy." (PMID 31862442, 2020).
Dunnigan syndrome (25 papers, 2005 to 2025). "LMNA mutations causing classical familial partial lipodystrophy of Dunnigan type (FPLD2) usually affect residue R482." (PMID 39948343, 2025). "The accumulation of farnesylated prelamin A has been suggested as one of the mechanisms responsible for the loss of fat in type 2 familial partial lipodystrophy due to variants in the LMNA gene." (PMID 38279282, 2024). "Type 2 familial partial lipodystrophy (FPLD2) is a laminopathic lipodystrophy due to pathogenic variants in the LMNA gene." (PMID 36899861, 2023). "Dunnigan syndrome is an autosomal dominant disease caused by pathogenic variants in the LMNA gene encoding lamin A/C, a protein of the nuclear envelope." (PMID 35440056, 2022). "The Dunnigan-type familial partial lipodystrophy is caused by mutations in the LMNA gene, located on the long arm of chromosome 1 (1q21–q22)." (PMID 35626278, 2022). "In most forms of Dunnigan syndrome, the genetic diagnosis reveals a heterozygous missense pathogenic variant of the LMNA gene." (PMID 35440056, 2022). "Familial partial lipodystrophy of the Dunnigan type (FPLD 2) is a rare autosomal dominant disorder caused by the mutations of the lamin A/C gene leading to the defective adipogenesis, premature death of adipocytes and lipotoxicity." (PMID 26976018, 2016). "Other LMNA gene mutations, such as Dunnigan-type familial partial lipodystrophy (FPLD2), can lead to proatherogenic metabolic disturbances such as dyslipidemia, hyperinsulinemia, hypertension and diabetes." (PMID 21711540, 2011). "Nuclear abnormalities in fibroblasts from our subject with HGPS also differed from those reported in fibroblasts from subjects with Dunnigan-type familial partial lipodystrophy, a condition caused by different autosomal dominant LMNA mutations." (PMID 15982412, 2005). "Type 2 familial partial lipodystrophy (FPLD2) is a laminopathic lipodystrophy that may recognize different mutations within the LMNA gene." (PMID 39470804, 2025). "While familial partial lipodystrophy type 1 is likely a multigenic form of lipodystrophy syndrome, familial partial lipodystrophy type 2, caused by pathogenic variants in the LMNA gene, represents the most common genetically determined form of partial lipodystrophy." (PMID 39944202, 2025). "Among 29 patients with FPLD, 12 had typical Dunnigan syndrome due to heterozygous LMNA variants." (PMID 39352627, 2025). "Type-2 Familial Partial Lipodystrophy is caused by LMNA mutations." (PMID 31375660, 2019). "The most common type is the Dunnigan variant or familial partial lipodystrophy type 2 (FPLD2), which is inherited in an autosomal dominant manner and is caused by variants of the LMNA gene on chromosome 1q21-22." (PMID 38633761, 2024). "The most frequent FPLD is the Dunnigan syndrome, also referred to as type 2 FPLD (FPLD2), which occurs due to pathogenic variants in the LMNA gene." (PMID 36354755, 2022). "Dunnigan syndrome, or Familial Partial Lipodystrophy type 2 (FPLD2; ORPHA 2348), is a rare autosomal dominant disorder due to pathogenic variants of the LMNA gene." (PMID 35440056, 2022). "Not all patients with symptoms suggestive of Dunnigan syndrome carry a pathogenic variant in the LMNA gene." (PMID 35440056, 2022). "Type 2 familial partial lipodystrophy (FPLD2; MIM: #151660) or Dunnigan disease results from heterozygous or compound heterozygous variants affecting mainly exons 8 and 11 of LMNA gene (1q21–22, NC_000001.11), although variants in other exons have been reported." (PMID 29557732, 2018).
Ventricular arrhythmia (25 papers, 2013 to 2025). "Mutations in the LMNA gene have been linked to atrioventricular block and atrial or ventricular arrhythmias." (PMID 36917398, 2023). "Of the patients with diagnostic variants, 15.8% (81/514) had a variant in genes that have been associated with increased risk of ventricular arrhythmias (LMNA, RBM20, FLNC, and PLN)." (PMID 37795486, 2023). "As the previous papers reported, conduction disorder and ventricular arrhythmia are also the characteristics of DCM with LMNA mutation." (PMID 34250035, 2021). "Telemetric and in vivo electrophysiological studies in 10-week-old Lmna Δ8-11 +/− mice showed AV conduction defects and both atrial and ventricular arrhythmias, analogous to those observed in humans with heterozygous LMNA mutations." (PMID 29619865, 2018). "In this study, the majority of LMNA mutation-positive subjects had ventricular arrhythmias and/or conduction system defects, including severe arrhythmic phenotypes, such as sustained VT and complete AV block, while cardiac function was variable." (PMID 25837155, 2015). "Furthermore, it was also revealed that patients with LMNA mutations were predisposed to develop fatal ventricular arrhythmias as well as severe heart failure." (PMID 36950287, 2023). "For example, mutations in LMNA and PLN have been associated with a higher prevalence of ventricular arrhythmias and sudden cardiac death than those in sarcomeric genes." (PMID 40080479, 2025). "Mutations in genes such as LMNA, PLN, RBM20, and FLNC are associated with an increased risk of ventricular arrhythmias (VA) and SCD." (PMID 40711538, 2025). "Lamin A/C gene (LMNA) mutations present with various symptoms, but women with LMNA heart disease are less likely to have life-threatening ventricular arrhythmias, suggesting male sex is a risk factor." (PMID 37504533, 2023). "A key nuclear lamina protein is nuclear Lamin type A, which is encoded by the LMNA gene, and LMNA mutations cause DCM, conduction defects and ventricular arrhythmias." (PMID 36189811, 2022). "Human mutations in TMEM43, LMNA, and LEMD2 have been associated with often highly penetrant, aggressive disease with respect to ventricular arrhythmia and sudden cardiac death." (PMID 32670084, 2020). "Furthermore, a recent study reported that not only LMNA gene mutations, but also DSP, PKP2, and FLNC gene mutations in DCM cases are likely to cause sudden death and ventricular arrhythmia, supporting the usefulness of genetic testing in the clinical testing." (PMID 36950287, 2023). "Atrial fibrillation, AV-block, ventricular arrhythmias and non-sustained ventricular tachycardia are frequent even among asymptomatic LMNA mutations carriers." (PMID 31208058, 2019). "Of note, one of the most studied genes is lamin A/C (LMNA), where life-threatening ventricular arrhythmias can occur, even without significant LV impairment." (PMID 36836107, 2023).
partial lipodystrophy (21 papers, 2012 to 2025). Loss and redistribution of subcutaneous and/or visceral adipose tissue from specific regions of the body. "A notable phenotypic difference lies in the specific association of LMNA variants with partial lipodystrophy (MADA) and ZMPSTE24 variants with generalised lipodystrophy (MADB)." (PMID 39273270, 2024). "Individuals reported in the studies included 90 with partial lipodystrophy (72 due to LMNA mutation and 15 due to PPARG mutation), 42 with generalized lipodystrophy (21 AGPAT2, 21 BSCL2, 2 LMNA), and 19 with IR due to INSR mutation(s)." (PMID 37794082, 2023). "We herein report the clinical history of two patients affected by APS and partial lipodystrophy due to LMNA p.R349W mutation who displayed mild COVID-19 symptoms and were not hospitalized." (PMID 35384599, 2022). "The third patient, having mutation in exon 1 of the LMNA gene, had partial lipodystrophy and congestive heart failure with conduction defect, but the first signs of cardiac disease occurred later than in our patient, i.e. in the fifth decade of life." (PMID 27585670, 2017). "Familial partial lipodystrophy tends to be associated with functional mutations in the LMNA (lamin A/C) gene resulting in altered adipose tissue distribution." (PMID 27312935, 2016). "MADA with partial lipodystrophy, more marked acral, can be caused by homozygous or compound heterozygous mutation in the gene encoding lamin A and lamin C (LMNA)." (PMID 25286833, 2014). "FPLD2 is typical partial lipodystrophy caused by mutations in the LMNA gene." (PMID 30781376, 2019). "These rare single nucleotide variants have been previously associated with dominant limb-girdle muscular dystrophy (Emery-Dreifuss muscular dystrophy 2) and partial lipodystrophy, and reported to affect lamin A/C function by in vitro studies." (PMID 39669119, 2024). "Familial partial lipodystrophy with mandibuloacral dysplasia (MAD), on the other hand, is a rare autosomal recessive disease that is due to mutations in the lamin A/C gene (LMNA) and mutations in the zinc metalloproteinase gene (ZMPSTE24)." (PMID 33233602, 2020). "We report a non-familial (sporadic) case of partial lipodystrophy caused by a novel genetic mechanism involving closely linked de novo pathogenic variants in the LMNA gene." (PMID 39669119, 2024). "Familial partial lipodystrophy of the Dunnigan type (also called type 2 familial partial lipodystrophy, FPLD2, OMIM # 151660) is a rare genetic disease due to heterozygous mutations in the LMNA gene encoding lamin A/C." (PMID 37998321, 2023).
mandibuloacral dysplasia (20 papers, 2013 to 2022). Mandibuloacral dysplasia (MAD) is a rare genetic bone disorder characterized by growth delay, postnatal development of craniofacial anomalies including mandibular hypoplasia, progressive acral osteolysis, mottled or patchy pigmentation, skin atrophy, and partial or generalized lipodystrophy. "Additionally, the autosomal recessive mutation of LMNA gene is related to mandibuloacral dysplasia (MAD), which causes changes in lipid metabolism." (PMID 35281936, 2022). "Mandibuloacral dysplasia is an extremely rare autosomal recessive progeroid syndrome due to mutations in genes encoding nuclear lamina proteins, lamins A/C (LMNA) or prelamin A processing enzyme, and zinc metalloproteinase (ZMPSTE24) which has been reported in approximately 40 case reports." (PMID 32056035, 2020). "Progeroid features are also observed in mandibuloacral dysplasia caused by LMNA mutations." (PMID 29861492, 2018). "Hyperactivation of S6K has also been observed in adipocyte precursor and osteosarcoma cell lines expressing LMNA mutations associated with Type 2 Familial Partial Lipodystrophy (FPLD2) and Mandibuloacral Dysplasia (MADA), respectively." (PMID 34453483, 2021). "In 2002, a link between mandibuloacral dysplasia (MAD) and LMNA mutations was demonstrated." (PMID 29861492, 2018). "Patients affected by Mandibuloacral Dysplasia (MADA), a progeroid disease linked to LMNA mutations, suffer from an osteolytic process." (PMID 25823658, 2015).